KIF26B-AS1 (KIF26B antisense RNA 1)
Synonyms: RP11-62I21.1
Gene: Long non-coding RNA gene on chromosome 1 (245,206,444 to 245,234,501, reverse strand). Ensembl gene ENSG00000232192.
Diseases named in the same sentence as KIF26B-AS1 in open-access papers:
KIF26B-AS1 is named in the same sentence as 1 disease in open-access papers, as found by Europe PMC text mining. Sharing a sentence is not in itself a finding about the gene and the disease. The quoted sentences say what the papers report.
laryngeal carcinoma (2 papers, 2022 to 2024). Carcinoma that arises from the laryngeal epithelium. "In laryngeal cancer, KIF26B antisense RNA 1 regulates TLR4 and activates the TLR4 signaling pathway to promote malignant progression." (PMID 38463226, 2024). "The results showed that KIF26B antisense RNA 1 (KIF26B-AS1) propels cell proliferation and migration in laryngeal cancer and regulates the toll-like receptor 4 (TLR4) signaling pathway." (PMID 36224753, 2022).